FBXO22 (F-box protein 22)
Diseases named in the same sentence as FBXO22 in open-access papers (continued):
Sharing a sentence is not in itself a finding about the gene and the disease.
tumor (32 papers, 2015 to 2025). "Several studies have shown that FBXO22 is associated with tumor development and therapeutic response." (PMID 38296976, 2024). "F-box protein 22 (FBXO22) was found to be significantly upregulated in tumor tissues of 106 PDAC patients with poor prognosis by causing ubiquitin-dependent degradation of LATS, thus inhibiting the Hippo pathway." (PMID 38174069, 2023). "Lower expression of FBXO22 in RCC patients is associated with tumor size, TNM stage, and poor survival." (PMID 32793396, 2020). "Taken together, these results demonstrate that FBXO22 expression is upregulated in multiple cancers, implying that high FBXO22 expression levels may be associated with tumor progression." (PMID 35141150, 2021). "In liver cancer, FBXO22 enhances tumor formation and progression by promoting the degradation of p21, a cell cycle regulator." (PMID 40534867, 2025). "Conversely, oncogenic F-box proteins such as SKP2 and FBXO22 promote cancer cell proliferation and metastasis by degrading tumor suppressors or stabilizing hypoxia-inducible factors, respectively." (PMID 40534867, 2025). "For instance, FBXO22 upregulation in HCC promotes tumor growth and proliferation by mediating p21 ubiquitination and degradation." (PMID 41387673, 2025). "Recently, FBXO22 was reported to be critically involved in immunotherapy by targeting programmed death‐ligand 1 (PD‐L1) in tumour cells." (PMID 39153212, 2024). "Accumulating evidence has demonstrated that F‐box protein 22 (FBXO22) participates in tumour development and progression in various types of human malignancies." (PMID 39153212, 2024). "FBXO22 promotes PD‐L1 degradation via an ubiquitination and leads to increased tumour cell sensitivity to DNA damage in NSCLC." (PMID 39153212, 2024). "Similar to the action of SPOP, FBXO22 directly ubiquitinates and degrades PD-L1, thereby increasing the sensitivity of tumor cells to immunotherapeutic agents." (PMID 39315102, 2024). "Accumulating evidence has indicated that F‐box protein 22 (FBXO22) participates in tumour development and progression in various types of human malignancies." (PMID 39153212, 2024). "We found that FBXO22 was significantly highly expressed in tumor tissues, in line with the outcomes of the TCGA and CGGA analyses." (PMID 38519492, 2024). "Radiation induces upregulation of PDL1 expression and thus confers immunosuppression within the tumor, which can be reversed by FBXO22-mediated PDL1 degradation, resulting in a slowdown of growth in FBXO22-overexpressing cells." (PMID 38296976, 2024). "More importantly, in the tumor xenograft model of nude mice, sgFBXO22 combined with IR showed a notable reduction in tumor size compared with the IR group, indicating that FBXO22 knockout also exerts a synergistic effect of radiotherapy in vivo." (PMID 38296976, 2024). "Among ER-positive and HER2-negative BCs with invasive ductal carcinoma (IDC), a low level of Fbxo22 in tumor tissues predicted a poorer outcome in our clinical cohort." (PMID 38180699, 2024). "Our study validated FBXO22 as a tumor suppressor in TNBC through ubiquitination of KDM5A and regulation of p16." (PMID 36112263, 2023). "Functionally, ectopic expression of FBXO22 promoted cell viability in vitro and induced tumor growth in vivo, while knockdown of FBXO22 exhibited opposite effects." (PMID 36127346, 2022). "The expression of FBXO22 protein in CC tissues was higher than that in adjacent non-tumor cervical tissues." (PMID 36127346, 2022). "The role of FBXO22 as a tumor driver is supported by the frequent overexpression of this protein in cancer, and by xenograft models, where FBXO22 expression promotes tumorigenesis by degradation of nuclear PTEN." (PMID 36428706, 2022). "Conversely, overexpression of FBXO22 resulted in an increased tumor growth rate and terminal tumor weight." (PMID 36127346, 2022).
tumor (continued). "FBXO22 has been identified to be critically involved in regulating the ubiquitination of substrate proteins, thus regulating tumor progression." (PMID 35141150, 2021). "Taken together, this evidence suggests that tumor FBXO22 expression plays an important role in tumor immune regulation." (PMID 35141150, 2021). "Our analysis provided a relatively comprehensive understanding of the oncogenic role of FBXO22 in different tumor types." (PMID 35141150, 2021). "GSE62452 demonstrated that the higher expression levels of FBXO1, FBXO20, FBXO32, and FBXO45 were correlated with poorer tumor differentiation (N = 68), apart from FBXO22 and FBXO38." (PMID 35046938, 2021). "FBXO22 can reverse cisplatin resistance in tumor cells by mediating polyubiquitination and degradation of basigin (BSG, also known as CD147) through its recognition of the BSG intracellular domain." (PMID 35141150, 2021). "All these results support that FBXO22 promotes tumor growth through K221 ubiquitylation-mediated degradation of nuclear PTEN." (PMID 32249768, 2020). "The mRNA levels of FBXO22 were significantly increased in various types of human tumor tissues compared to that in normal tissues." (PMID 32793396, 2020). "It is important to notice that F-box proteins, including FBXO22, have oncogenic or tumor suppressive role in cancer development and progression." (PMID 32793396, 2020). "Sustained Nrf2 activation upregulates home oxygenase-1 (Ho-1) that catabolizes free heme, causing functional inactivation of ubiquitin ligase Fbxo22 and the subsequent stabilization of BACH1 and tumor cell metastasis." (PMID 32226544, 2020). "Recently, circular RNA (circRNA) circ_0006282 was revealed to facilitate tumor progression via sponging miR-155 to increase FBXO22 expression in gastric cancer." (PMID 32793396, 2020). "Multivariate analysis showed that tumor size and the positive expression of FBXO22 were independent prognostic indicator of OS." (PMID 30808376, 2019). "Especially, Multivariate analysis showed that tumor size and the expression of FBXO22 were independent prognostic indicator of OS (95% CI: 1.077–5.157, P<0.05)." (PMID 30808376, 2019). "It was also found that tumor size and the expression of FBXO22 were independent prognostic indicator of OS and the expression of FBXO22 and p21 was negatively correlated in clinical samples." (PMID 30808376, 2019). "Because FBXO22 plays an important role during tumor progression, we tested the levels of proteins related to signaling pathways and the cell cycle." (PMID 30808376, 2019). "Knockdown of FBXO22 inhibited cell growth in vitro and tumor formation in nude mice, while overexpression of FBXO22 increased cell viability." (PMID 30808376, 2019). "On univariate survival analysis, serum AFP, tumor size, BCLC stage, TNM stage, differentiation, vascular invasion, and expression of FBXO22 were associated with OS." (PMID 30808376, 2019). "The results indicate that FBXO22 is overexpressed in tumors compared to adjacent non-tumor tissues (p < 0.001, paired Student’s t-test)." (PMID 30808376, 2019). "To date, although there are few reports on the relationship between FBXO22 and tumor, the role of FBXO22 in tumorigenesis remains debatable." (PMID 31217475, 2019). "Multivariate analysis showed that tumor size and the expression of FBXO22 were independent prognostic indicator of OS." (PMID 30808376, 2019). "On univariate survival analysis, the factors significantly associated with OS were serum AFP, tumor size, BCLC stage, TNM stage, differentiation, vascular invasion and positive expression of FBXO22." (PMID 30808376, 2019). "Western blot analysis showed that the expression level of FBXO22 in the tumor group was significantly higher than that in the non-tumor liver group (30 of 50 cases) (respectively)." (PMID 30808376, 2019). "The expression of FBXO22 was significantly increased in tumor samples compared with adjacent normal tissue." (PMID 26087183, 2015).
tumor (continued). "Consistently, in FBXO22 overexpressed tumor tissues, the expression levels of p21Cip1/WAF1, and Cyclin B1 were also affected." (PMID 26087183, 2015). "KLF4 protein contents were reduced in FBXO22 overexpressed tumor tissues, suggesting an oncogenic role of FBXO22 in vivo." (PMID 26087183, 2015). "In agreement, the tumor volume and weight were markedly increased in FBXO22-overexpressed tumors compared to control tumors." (PMID 26087183, 2015). "Like most FBXO proteins, FBXO22 contains the F-box domain in the N-terminus and protein–protein interaction domains for substrate recognition in the C-terminus and FBXO22 has been shown to regulate tumor progression and metastasis by targeting key regulators like BACH1." (PMID 40263598, 2025). "These in vivo data suggested that FBXO22-mediated VHL degradation can promote GBM tumor growth." (PMID 38519492, 2024). "We observed that FoxO1 expression was upregulated in FBXO22‐knockdown xenograft tumour tissues." (PMID 39153212, 2024). "Moreover, we conducted Western blotting analysis to measure the expression of FoxO1 and FBXO22 in xenograft tumours." (PMID 39153212, 2024). "To validate this finding, we used nude mice to determine whether FBXO22 depletion in SaOS‐2 cells retarded tumour growth in vivo." (PMID 39153212, 2024). "We observed that FBXO22 knockdown inhibited the growth of tumour xenografts in mice." (PMID 39153212, 2024). "Similarly, reduced activity of the F-box protein, FBXO22, contributes to tumor progression and metastasis in lung and breast cancers by increasing levels of key oncogenic factors such as Bach1, HDM2 and SNAIL." (PMID 38155930, 2023). "Mechanistically, FBXO22 physically interacted with the cyclin-dependent kinase inhibitor p57Kip2 and subsequently mediated its ubiquitination and proteasomal degradation leading to tumor progression." (PMID 36127346, 2022). "The expression of FBXO22 in human CC tissues was higher than that in adjacent non-tumor tissues." (PMID 36127346, 2022). "The expression of FBXO22 and p57Kip2 in the mouse xenograft tumor tissues was analyzed by IHC." (PMID 36127346, 2022). "These lines of evidence suggest that the expression level and genetic alterations of FBXO22 in the tumor may influence antitumor immunity." (PMID 35141150, 2021). "Finally, we analyzed the correlation between the abundance of tumor infiltrating lymphocytes (TILs) and FBXO22 expression, copy number variation, and methylation." (PMID 35141150, 2021). "FBXO22 regulates the levels of these proteins to alter tumor progression." (PMID 35141150, 2021). "FBXO22 plays a tumor-promoting role by ubiquitylating and degrading nuclear PTEN." (PMID 32249768, 2020). "However, it not only resisted the ubiquitylation and degradation of PTEN by FBXO22, but also almost completely suppressed the tumor-promoting role of FBXO22." (PMID 32249768, 2020). "DOX administration induced tumoral FBXO22 overexpression and promoted tumor growth." (PMID 32249768, 2020). "FBXO22 is critically involved in tumorigenesis and tumor progression." (PMID 32793396, 2020). "F-Box protein FBXO22 could mediate the polyubiquitination and degradation of CD147 by interacting with CD147, and CD147 polyubiquitination by FBXO22 reversed cisplatin resistance of tumor cells." (PMID 29163835, 2017). "FBXO22 emerges as a critical gene conferring chemotherapeutic sensitivity to tumor cells." (PMID 28117675, 2017). "Therefore, FBXO22 knockdown inhibited tumour growth in mice." (PMID 39153212, 2024). "Although many studies have shown that FBXO22 is involved in oncogenesis owing to its ubiquitination activity and the subsequent degradation of multiple proteins, the means by which FBXO22 affects tumor growth by regulating substrate protein levels was largely unknown." (PMID 35141150, 2021).
tumor (continued). "Moreover, both in vitro and in vivo experiments showed that knocking down FBXO22 expression could inhibit cell proliferation, while overexpression of FBXO22 promoted tumor formation." (PMID 30808376, 2019). "In contrast to FBXO9, whose expression is downregulated in AML patients compared to healthy controls and acting as a tumor suppressor in AML, FBXO22 is highly expressed in AML, especially MLLr AML patients." (PMID 36774506, 2023). "FBXO22 was shown to promote proliferation, migration, and invasion of HCC cells and facilitated their tumor growth in vivo." (PMID 36127346, 2022). "In consistence with its tumor-promoting role through downregulating nuclear PTEN, FBXO22 was overexpressed in most types of cancers." (PMID 32249768, 2020). "To evaluate the role of FBXO22 on tumorigenesis, we showed that knockdown of FBXO22 in SW620 cells by shRNA dramatically suppressed subcutaneous tumor growth." (PMID 32249768, 2020). "We continued to verify the connection between FBXO22-mediated nuclear PTEN degradation and the tumor-promoting role of FBXO22, by utilizing the PTENK221R mutant." (PMID 32249768, 2020). "FBXO22 targets HDM2 for ubquitination and degradation, leading to inhibitory effects on invasion and metastasis in breast cancer." (PMID 32793396, 2020). "Taken together, these results suggest that FBXO22 promotes HCC cell proliferation in vitro and tumor growth in vivo." (PMID 30808376, 2019). "In this study, we explored the role of FBXO22 in HCC and its mechanism of promoting tumor development." (PMID 30808376, 2019). "Overexpression of FBXO22 was detected in 61.8% (68/110) of HCC patients and was significantly correlated with serum AFP (p = 0.003), tumor size (p = 0.019), and vascular invasion (p = 0.031)." (PMID 30808376, 2019). "Given that KLF4 appears to function as a tumor suppressor in HCC, we next determined what physiologically stimulates FBXO22 to interact with and stabilize KLF4." (PMID 26087183, 2015). "Fbxo22 negativity was correlated with negative PgR status but not with high Ki-67 positivity, lymph node involvement, or tumor grade." (PMID 38180699, 2024). "While numerous oncogenes have been identified as enhancers of tumor metastasis through the promotion of EMT, a subset of oncogenes, such as CREB1, MYC and FBXO22 (F-box protein 22), has been observed to concurrently facilitate proliferation while inhibiting EMT." (PMID 39883338, 2024). "We also confirmed this negative correlation between FBXO22 and p57Kip2 in the xenograft tumors by Western blotting for the two proteins in tumor tissue extracts." (PMID 36127346, 2022). "The statistic results show that negative or positive FBXO22 expression accounted for 68.9% or 31.1% of the 251 tumor samples analyzed, respectively." (PMID 34950036, 2021). "We then asked whether the FBXO22-mediated inhibition of nuclear PTEN and its downstream signaling are connected to the tumor-promoting role of FBXO22." (PMID 32249768, 2020). "FBXO22 elevated proliferation of HCC cells and enhanced tumor growth in mice." (PMID 32793396, 2020). "The expression levels of FBXO22 among 110 HCC tumor samples and adjacent non-tumor tissues was compared using the IHC results." (PMID 30808376, 2019). "To conclude, our study demonstrated that FBXO22 mediated the polyubiquitination and degradation of CD147 by interacting with CD147-ICD, and CD147 polyubiquitination by FBXO22 reversed cisplatin resistance of tumor cells." (PMID 28117675, 2017).
tumor (continued). "One potential explanation regarding the difference in Fbxo22 negativity between ILC and IDC, especially ILC in postmenopausal women, might be the differential tumor microenvironment in terms of the estrogen signal transduction pathway between the two histological types." (PMID 38180699, 2024). "Tumor volume and weight measurements showed that no significant alterations were seen in tumor volume and weight as compared with the Flag-Fbxo22 group with the pCDH group, and compared with the Flag-Fbxo22 group with the Flag-Fbxo22 + HA-KDM5A group." (PMID 36112263, 2023). "This may be because, in a subset of cancer types, changes in FBXO22 expression levels alone are not sufficient to affect tumor progression, and genetic alterations in FBXO22 have a more pronounced effect on tumors." (PMID 35141150, 2021). "As for FBXO5, FBXO22, FBXO28, FBXO31 and FBXO45, they may be the independent poor prognostic factors of BC and the expression levels of which were closely related to different tumor stages." (PMID 33622332, 2021). "Notably, FBXO22 expression level is correlated with serum AFP, tumor size, and vascular invasion." (PMID 32793396, 2020). "The clinical data indicated that the lack of Fbxo22 expression resulted in a poorer outcome regardless of ILC or IDC, low Ki-67 expression, node-negative status, low tumor grade, or treatment with TAM." (PMID 38180699, 2024). "The FBXO22-induced downregulation of BACH1 promotes AML progression, which means that BACH1 has a negative effect on tumor growth in this context." (PMID 38321558, 2024). "As a result, unlike NEDD4-1 or WWP2, FBXO22 did not affect AKT activation, but negatively regulated nuclear PTEN functions, such as the activity of APC/C-CDH1 complex and alternative splicing, to play a tumor-promoting role." (PMID 32249768, 2020). "However, there was no statistical difference between FBXO22 expression levels and sex, age, ALT, AST, tumor number, BCLC stage, TNM stage, differentiation, tumor capsule and recurrence." (PMID 30808376, 2019).